IL13RA2 (interleukin 13 receptor subunit alpha 2)
Diseases named in the same sentence as IL13RA2 in open-access papers (continued):
Sharing a sentence is not in itself a finding about the gene and the disease.
osteosarcoma (5 papers, 2023 to 2025). A usually aggressive malignant bone-forming mesenchymal neoplasm, predominantly affecting adolescents and young adults. "Positivity for IL-13Rα2 was associated with a 7.191-fold increased risk of mortality in osteosarcoma patients (95% CI: 2.063–25.067; p = 0.002) and a 6.616-fold increased likelihood of tumor relapse or patient death (95% CI: 1.909–19.883; p = 0.002)." (PMID 39598436, 2024). "Considering that IL-13Rα2 is associated with reduced survival in osteosarcoma patients who received adjuvant chemotherapy, these findings suggest a potential role for IL-13Rα2 in resistance to standard anticancer treatments." (PMID 39598436, 2024). "In this study, beyond the prognostic relevance of IL-13Rα2 expression in osteosarcoma patients, IL-13Rα2 expression showed a close association with the proliferation and invasion activity of osteosarcoma cells." (PMID 39598436, 2024). "Therefore, the shift towards an antiapoptotic state by IL-13Rα2 overexpression likely underlies the resistance to doxorubicin-induced cell death in osteosarcoma." (PMID 39598436, 2024). "In addition, the expression of IL-13Rα2 was associated with osteosarcoma cell proliferation and invasiveness." (PMID 39598436, 2024). "Therefore, we hypothesized that IL-13Rα2 might be associated with therapeutic efficacy for the conventional treatment of osteosarcoma, and we further analyzed the 26 patients who had received postoperative chemotherapy." (PMID 39598436, 2024). "This study showed that elevated IL-13Rα2 expression correlates with reduced survival rates in osteosarcoma patients." (PMID 39598436, 2024). "In osteosarcoma patients who received adjuvant chemotherapy, higher expression of IL-13Rα2 predicted shorter survival." (PMID 39598436, 2024). "In this context, IL-13Rα2 contributes to the resistance to doxorubicin, a commonly used chemotherapeutic agent in osteosarcomas." (PMID 39598436, 2024). "Univariate analysis showed that osteosarcoma patients with higher IL-13Rα2 expression have significantly shorter OS and RFS." (PMID 39598436, 2024). "Based on the role of IL-13Rα2 expression in the prognosis of osteosarcoma, the effects of IL-13Rα2 on the proliferation of osteosarcoma cells were evaluated." (PMID 39598436, 2024). "Considering the therapeutic implication of overcoming resistance to anticancer cytotoxic agents of osteosarcomas, the impact of IL-13Rα2 knockdown or overexpression on cell proliferation and apoptosis in response to doxorubicin treatment was evaluated." (PMID 39598436, 2024). "IL-13Rα2-overexpressing osteosarcoma cells were resistant to doxorubicin, as evidenced by higher cell proliferation and the colony-forming ability of cells and in vivo tumor growth in mice under treatment with the drug." (PMID 39598436, 2024). "This association remains significant even after adjusted in multivariate analysis with other clinical factors such as age, tumor size, stage, and metastatic status, suggesting that IL-13Rα2 is an independent prognostic indicator in osteosarcoma." (PMID 39598436, 2024). "Osteosarcoma cells with a knockdown of IL-13Rα2 were more sensitive to doxorubicin-mediated cytotoxicity in a CCK-8 assay." (PMID 39598436, 2024). "Overexpression of IL-13Rα2 significantly increased osteosarcoma cell proliferation, migration, and invasion, while knockdown of IL-13Rα2 suppressed these activities." (PMID 39598436, 2024). "In osteosarcoma tissues, immunohistochemical staining revealed IL-13Rα2 in both the cytoplasm and nuclei of osteosarcoma cells." (PMID 39598436, 2024). "In U2OS and KHOS/NP osteosarcoma cells, overexpression of IL-13Rα2 significantly increased proliferation, migration, and invasion of cells, all of which decreased with knockdown of IL-13Rα2." (PMID 39598436, 2024). "In line with the effect of IL-13Rα2 on osteosarcoma cell growth and invasion, it also plays a role in signaling pathways related to cell proliferation, invasion, and apoptosis." (PMID 39598436, 2024).
osteosarcoma (continued). "Therefore, this study aimed to investigate the expression and roles of IL-13Rα2 in the progression of osteosarcoma." (PMID 39598436, 2024). "Doxorubicin was less effective in osteosarcoma cells overexpressing IL-13Rα2." (PMID 39598436, 2024). "In addition, both in vitro and in vivo, proliferation of osteosarcoma cells increased, and apoptosis decreased with overexpression of IL-13Rα2 under treatment with doxorubicin." (PMID 39598436, 2024). "In conclusion, findings from this study indicate that IL-13Rα2 could serve as a novel marker of poor prognosis in osteosarcoma patients." (PMID 39598436, 2024). "Knockdown of IL-13Rα2 sensitized osteosarcoma cells to the cytotoxic effect of doxorubicin." (PMID 39598436, 2024). "Therefore, based on these results, the impact of IL-13Rα2 on osteosarcoma cell survival during doxorubicin treatment was further evaluated." (PMID 39598436, 2024). "Besides its roles in osteosarcoma cell proliferation and invasiveness, IL-13Rα2 also plays a role in the regulation of signaling pathways related to cell survival and apoptosis." (PMID 39598436, 2024). "This distinction is crucial to employ IL-13Rα2 as a therapeutic target of osteosarcoma." (PMID 39598436, 2024). "Considering the prognostic impact of IL-13Rα2 in osteosarcoma, it is suggested that IL-13Rα2 expression might be associated with molecular mechanisms of cancer progression." (PMID 39598436, 2024). "Considering the role of IL-13Rα2 in cancer progression and the effectiveness of blocking IL-13Rα2-related pathways in inhibiting and deteriorating cancer cells, IL-13Rα2 might be a potential therapeutic target for osteosarcoma." (PMID 39598436, 2024). "Nonetheless, research on IL-13Rα2 in sarcomas, particularly osteosarcoma, remains limited." (PMID 39598436, 2024). "Given the role of TGF-β in EMT activation through the regulation of snail and ZEB gene expression, the increased invasiveness of IL-13Rα2-overexpressing osteosarcoma cells might be correlated to the EMT phenotype of cells." (PMID 39598436, 2024). "Furthermore, overexpression of IL-13Rα2 induced resistance to doxorubicin, and the knockdown of IL-13Rα2 sensitized osteosarcoma cells to doxorubicin." (PMID 39598436, 2024). "Therefore, patients with osteosarcoma, particularly osteosarcomas with high IL-13Rα2 expression, may benefit from a novel therapeutic approach targeting this protein." (PMID 39598436, 2024). "Therefore, it is suggested that IL-13Rα2 expression might be used as a prognostic indicator of human cancers, including osteosarcomas." (PMID 39598436, 2024). "In addition, overexpression of IL-13Rα2 in osteosarcoma cells inhibited pre-apoptotic signaling." (PMID 39598436, 2024). "Therefore, a therapeutic trial targeting IL13Rα2 might be a new therapeutic strategy for osteosarcoma, especially those highly expressing IL13Rα2." (PMID 39598436, 2024). "Therefore, osteosarcoma patients with shorter survival with elevated expression of IL-13Rα2 might benefit from IL-13Rα2-targeted immunotherapy." (PMID 39598436, 2024). "However, studies on the role of IL-13Rα2 in osteosarcoma are limited." (PMID 39598436, 2024). "Knockdown of IL-13Rα2 reduced protein and mRNA levels of cyclin D1, snail, TGF-β, and BCL2, while increasing BAX expression in osteosarcoma cells." (PMID 39598436, 2024). "Therefore, despite limited reports on the therapeutic efficacy of IL-13Rα2 in sarcomas, inhibition of IL-13Rα2 might enhance the efficacy of doxorubicin and potentially other chemotherapeutic agents, thereby improving outcomes for osteosarcoma patients with high IL-13Rα2 expression." (PMID 39598436, 2024). "In addition, when considering the role of IL-13Rα2 in bone homeostasis and its dysregulation in osteosarcoma, comparing it with non-cancerous cells is essential to distinguish tumor-specific dysregulation from normal physiological processes." (PMID 39598436, 2024).
osteosarcoma (continued). "Therefore, further study is needed to provide valuable insights into whether IL-13Rα2 represents a viable, specific therapeutic target for osteosarcoma, rather than solely a prognostic marker." (PMID 39598436, 2024). "Furthermore, IL-13Rα2 positivity was an independent indicator of shorter OS (HR: 11.985; 95% CI: 2.600–55.254; p = 0.001) and RFS (HR: 7.461; 95% CI: 1.946–28.605; p = 0.003) for osteosarcoma patients who had received adjuvant chemotherapy in multivariate analysis." (PMID 39598436, 2024). "Most gene targets commonly investigated in ACT of other solid tumors except osteosarcoma, such as CEACAM1, PSCA, MSLN, IL13RA2, and GPC3, showed low or nonspecific expression in osteosarcoma compared with adjacent normal tissues." (PMID 37457661, 2023).
allergic asthma (4 papers, 2005 to 2023). A asthma with a basis in a pathological type I hypersensitivity reaction. "At baseline, we observed that VSG mice had increased circulating levels of IL-13Rα2, a negative regulator of type 2 cytokine signaling and allergic asthma responses." (PMID 36926031, 2023). "Indeed, IL-13Ra2 has been shown to contribute to allergic asthma and plays a unique role in the function of conventional pulmonary dendritic cells." (PMID 33050608, 2020).
metastatic tumors (4 papers, 2015 to 2021). "Low IL-13Rα2 expression (n = 6) was associated with a 33% survival rate of ACC subjects with tumor metastasis while ACC subjects without metastatic tumors (n = 20) showed a 100% survival rate (p = .001)." (PMID 33591997, 2021). "Therefore, the discovery of IL13Rα2 as an important mediator of metastatic disease in a subset of aggressive BLBCs should be further evaluated both as a biomarker and as a potentially important therapeutic target for preventing cancer metastasis." (PMID 26208975, 2015). "Similarly, high (n = 6) IL-13Rα2 expression was associated with 16.7% survival rate of ACC subjects with tumor metastasis along with a survival rate of 60% for subjects without metastatic tumors (n = 20) (p = .1602)." (PMID 33591997, 2021). "Instead, metastasis occurred at an even rate between all three expression levels; the metastatic tumor incidence was 23% in ACC subjects with low IL-13Rα2 expression, 20% in ACC subjects with medium IL-13Rα2 expression, and 23% in ACC subjects with high IL-13Rα2 expression." (PMID 33591997, 2021).
sarcoma (4 papers, 2010 to 2024). A usually aggressive malignant neoplasm of the soft tissue or bone. "Among sarcoma types, higher expression of IL-13Rα2 in malignant peripheral nerve sheath tumors has been reported, and a therapeutic approach targeting IL-13Rα2 showed suppression of tumor growth and elongation of survival time in a murine tumor model." (PMID 39598436, 2024). "The primary tumor cultures seem to have an intermediate expression of IL-13Rα2 where the IC50 for these cells is similar to the murine sarcoma cell line MCA304, which has moderate sensitivity to IL-13-PE." (PMID 23421960, 2013).
brain cancer (3 papers, 2023 to 2025). A primary or metastatic malignant neoplasm affecting the brain. "IL13RA2, a high-affinity receptor for IL13, is highly expressed in primary brain cancers, many extracranial solid tumors, and in lung- and brain-seeking metastatic variant cell lines." (PMID 40663259, 2025). "A comprehensive understanding of IL13Ra2 expression in BSG tumor samples is paramount since it will facilitate the development and improvement of immunotherapy against this deadly brain cancer." (PMID 38201655, 2024). "We have previously shown, both preclinically and clinically, that locoregional delivery of IL13Rα2-CAR T cells was safe and effective at eliminating malignant brain tumors." (PMID 36968221, 2023).
head and neck cancer (3 papers, 2013 to 2024). A primary or metastatic malignant neoplasm affecting the head and neck. "In previous studies, we analyzed IL-13Rα2 expression by immunohistochemistry and RT-PCR in tumors derived from patients with ovarian and head and neck cancer." (PMID 33591997, 2021). "We have previously reported that IL-13Rα2, a receptor that binds IL-13 with high affinity, is uniquely overexpressed on some human head and neck cancers." (PMID 23421960, 2013). "IL-13-PE has been shown to have cytotoxic effects against head and neck cancer cell lines that are either positive for IL-13Rα2 or are stably transfected to express IL-13Rα2." (PMID 23421960, 2013).
inflammatory bowel disease (3 papers, 2018 to 2024). A spectrum of small and large bowel inflammatory diseases of unknown etiology. "Previous research on patients with inflammatory bowel disease (IBD) has identified several genes (IL13RA2, TNFRSF11B, STC1, IL-6, and IL-11) that constitute potential biomarkers that can identify patients with limited response to IFX, which is consistent with our study." (PMID 34650991, 2021). "Similarly, in inflammatory bowel disease (IBD), fibroblasts contribute to inflammation through the secretion of factors like IL-11, IL-24, and IL-13RA2." (PMID 39290699, 2024).
neuroblastoma (3 papers, 2022 to 2025). Neuroblastoma (NB) is the most common solid, extracranial childhood tumor. "We found several peptides from proteins known to be dysregulated in DIPG, including IL13Rα2, PRAME, and MAGE, which are also known to generate strong, anti-tumor responses in neuroblastoma and acute myeloid leukemia." (PMID 37637064, 2023).
Pruritus (3 papers, 2023 to 2025). Pruritus is an itch or a sensation that makes a person want to scratch. "In response to associated pruritus, there is prominent scratching behavior that leads to basophil-dependent IL-4 upregulation, but may lead to increased expression of the IL-13-decoy receptor IL-13RA2 and interruption of the IL-4/IL-13 signaling cascade as well." (PMID 39126011, 2024). "The findings suggest a pivotal role of IL-4 and IL-13, along with IL-13RA1, in pruritus pathogenesis in both entities, while IL-13 upregulation in AD is countered by IL-13RA2." (PMID 39126011, 2024). "It appeared that TLR2 can upregulate peripheral IL-13Rα2 expression, which led to exaggeration of IL-13-mediated pruritus suggesting that peripheral TLR2-IL-13Rα2 signaling can cause itching sensation and enable neurogenic inflammation." (PMID 37834183, 2023). "Similarly, a positive correlation with pruritus NRS was observed for IL4R, CXCR1, TGFB1, IL13RA2." (PMID 41268562, 2025).
schistosomiasis (3 papers, 2008 to 2015). An infectious disease caused by parasitic trematodes of the genus Schistosoma that colonize human blood vessels and release eggs that can cause granulomatous reactions leading to acute (swimmer's itch or acute schistosomiasis syndrome) or chronic disease. "Intravenous injection of exogenous soluble IL-13Rα2 protein significantly reduces the volume of granulomas in IL-13Rα2 knockout mice with schistosomiasis." (PMID 26317423, 2015). "Our previous study shows enhanced IL-13Rα2 expression in primary macrophages of murine schistosomiasis." (PMID 26317423, 2015). "Because production of the soluble IL-13Rα2 is IL-4Rα-, IL-13Rα1-, and Stat6-dependent, these data combined with the schistosomiasis studies suggested that the Retnla−/− mice were developing stronger IL-4/IL-13 responses following infection." (PMID 19381262, 2009). "In this way, we hypothesize that IL-13Rα2 expressing macrophages contribute to the immunopathological development in schistosomiasis." (PMID 26317423, 2015). "The experiments using mice with macrophage specific knockout of IL-13Rα2 will help to unravel the causal role of macrophage IL-13Rα2 in S. japonicum egg-induced liver injury, despite global knockout of IL-13Rα2 aggravates granulomatous inflammation and reduces host survival in schistosomiasis." (PMID 26317423, 2015).
ulcerative colitis (3 papers, 2015 to 2022). An inflammatory bowel disease involving the mucosal surface of the large intestine and rectum. "Recent single-cell RNA-Seq data have shown an association between inflammatory-type fibroblasts (IL13RA2+-IL11+), IL-11, and Crohn’s disease and ulcerative colitis." (PMID 32897876, 2020).
atherosclerosis (2 papers, 2012 to 2021). A disease characterized by the build-up of fatty material and calcium deposition in the arterial wall resulting in partial or complete occlusion of the arterial lumen. "Hence, mice with knockout of CHI3L1 and/or IL-13Rα2 will more comprehensively illuminate the role of CHI3L1 in the initiation and progression of atherosclerosis and neovascularization in atherosclerotic plaques through the IL-13Rα2 pathway." (PMID 34349665, 2021).
brainstem glioma (2 papers, 2023 to 2024). "This compelling association underscores the promise of IL13Ra2 as a prime therapeutic target for treating brainstem glioma." (PMID 38201655, 2024). "Despite these limitations, our study sufficiently demonstrates the widespread expression of IL13Ra2 in brainstem gliomas and its close association with H3K27M, suggesting its potential as a therapeutic target for brainstem gliomas." (PMID 38201655, 2024). "The objective of this study was to investigate IL13Ra2 expression in brainstem glioma (BSG) and its correlation with key markers, functions, and prognostic implications, evaluating its therapeutic potential." (PMID 38201655, 2024). "Through multiplex immunofluorescence analysis, we unveiled a robust correlation between the widespread expression of the IL13Ra2 membrane antigen in brainstem glioma and the presence of the H3.3K27M antigen." (PMID 38201655, 2024). "Despite the challenges in various targeted therapies, ongoing research continues to advance, highlighting IL13Ra2 as a promising therapeutic target for brainstem gliomas." (PMID 38201655, 2024). "This study aimed to investigate the potential of IL13Ra2 as a therapeutic target in brainstem gliomas." (PMID 38201655, 2024).
fibrosarcoma (2 papers, 2022 to 2023). A malignant mesenchymal fibroblastic neoplasm affecting the soft tissue and bone. "The IL13 receptor family-negative human fibrosarcoma cell line HT1080 was engineered to overexpress IL13Rα2 (HT1080-IL13Rα2)." (PMID 35939683, 2022).
Granuloma (2 papers, 2015 to 2020). A compact, organized collection of mature mononuclear phagocytes, which may be but is not necessarily accompanied by accessory features such as necrosis. "Importantly, depletion of F4/80+CD11b+ macrophages after the injection of S. mansoni eggs reduced the size of granulomas, downregulated the expression of IL-13ra2 (IL-13Rα2), Retnla and Chi3l3 and affected CD4+ Th2 cell responses in the lung." (PMID 32922381, 2020).
injury (2 papers, 2016 to 2020). Damage inflicted on the body as the direct or indirect result of an external force, with or without disruption of structural continuity. "A previous study has demonstrated that IL-13 is a mediator, and possibly a therapeutic target, in radiation-induced lung injury, as shown by saturating fraction of the circulating decoy receptor IL-13Rα2." (PMID 33569004, 2020).